BDNF (brain derived neurotrophic factor)
Diseases named in the same sentence as BDNF in open-access papers (continued):
Sharing a sentence is not in itself a finding about the gene and the disease.
cancer (continued). "We found that the plasma BDNF levels were lower in cancer patients when compared to age-matched controls across all time points." (PMID 37770565, 2023). "In a study conducted with cancer patients currently undergoing treatment, it was also found that exercise led to an increase in BDNF levels." (PMID 37507961, 2023). "Beyond small molecule anti-cancer drugs, magneto liposomes also have been used to facilitate delivery of therapeutic peptide, brain-derived neurotrophic factor (BDNF) or antiretroviral agents across the BBB." (PMID 38139999, 2023). "Median plasma BDNF levels (ng/mL) among cancer participants were lower at baseline (10.7 vs 21.6, p < 0.001) and at 6 months from baseline (8.2 vs 15.3, p = 0.001) compared to non-cancer controls." (PMID 37770565, 2023). "A cascade of released substances follows, so that neurons release neurotransmitters, which in turn promote the secretion of NGF and BDNF from cancer cells." (PMID 36941697, 2023). "Physical activity levels are also related to higher BDNF expression, and newly diagnosed AYAC suffered from cancer‐related fatigue as well as limited by cancer‐induced mobility, which can impact the level of BDNF." (PMID 36221816, 2023). "Comparing the change in plasma BDNF levels from baseline to 6 months later, fewer cancer patients experienced a reduction of plasma BDNF levels as the number of Met alleles increased (Val/Val: 67%; Val/Met: 62%; Met/Met: 50%)." (PMID 37770565, 2023). "When stratifying BDNF trajectories by cancer treatments, a statistically significant reduction of BDNF levels was found among cancer patients receiving anthracyclines but not in other treatment types." (PMID 37770565, 2023). "VEGF-A and PDGF-BB were chosen for their crucial involvement in (neo)-angiogenesis, TGF-β2 as an inducer of EMT that is an important contributor to tumor cell heterogeneity in HNSCC, and BDNF as a neurotrophin involved in perineural invasion of cancer cells." (PMID 36544698, 2022). "TrkB activation by BDNF (or NAS) is a significant driver of cancer stem-like cell survival and proliferation." (PMID 36613754, 2022). "A previous report demonstrated that vascular endothelial cell-derived BDNF promotes cancer cell migratory ability." (PMID 36266462, 2022). "In contrast, the extracellular availability of NAS, being a BDNF mimic at TrkB, can aid the proliferation and survival of tumors and cancer stem-like cells." (PMID 36613754, 2022). "BDNF promoted cancer development by activating tropomyosin receptor kinase B (TrkB) in triple-negative breast cancer." (PMID 36619866, 2022). "In cancer biology, the expression of BDNF was found to be elevated in gliomas, breast cancer, colorectal cancer, gastric cancer, bladder cancer, and other human tumors." (PMID 36619866, 2022). "In agreement, loss of miR-204 results in BDNF/TRKB overexpression and activation of the Akt/mTOR/Rac1 signalling pathway, cancer cell migration and invasion in many cancers." (PMID 35158801, 2022). "A total of five cancer-related genes (BDNF, PTGS2, CTNNB1, GSK3B, and HPGD) were selected based on the Gene Ontology database." (PMID 35054980, 2022). "In colon cancer, BDNF promoted cancer progression by increasing the expression of HO-1 and transcription of VEGF, as well as the activation of the MAPK signaling pathway." (PMID 36619866, 2022). "In primary culture systems of patient-derived PGC cells and cancer-associated fibroblasts (CAFs), PGC cells co-cultured with CAFs exhibited significant upregulation of BDNF and epithelial-mesenchymal transition (EMT)." (PMID 36266462, 2022). "The role of BDNF/TrkB signaling has been assessed in cancer stem cell cultures derived from ADK cells of the lungs." (PMID 36289793, 2022). "This is likely due to the heterogeneity of cancer or treatment types, experimental design as well as the possible involvement of intermediary factors like BDNF." (PMID 33985854, 2021).
cancer (continued). "BDNF is important for the formation of new nervous tissue which assists in the development and progression of cancer as new nerve fibers assist in the expansion and migration of tumours." (PMID 34683450, 2021). "There are data demonstrating that BDNF-TrkB axis induce anoikis resistance in various cancer types, in addition to EMT." (PMID 34572400, 2021). "Although considerable studies have been conducted to understand the biological role of BDNF in various cancers over the past two decades, the functions of BDNF and its utility as a novel biomarker in PAAD have yet to be determined." (PMID 34777634, 2021). "In cancer biology, BDNF expression is increased in bladder cancer, glioma, gastric cancer, colorectal cancer, breast cancer, and other human malignancies." (PMID 33942699, 2021). "BDNF plays an important role in neuronal survival but is also involved in various cancers and is expressed by a variety of peripheral tissues and immune cells, such as eosinophils and neutrophils." (PMID 34771682, 2021). "At the cell detection level, the mRNA expression of BDNF was detected in most of the cancer cell lines, showing an increased tendency when compared to normal tissues." (PMID 34777634, 2021). "BDNF is known to stimulate growth of neurons and is important for the cancer related neurogenesis that is also involved in the invasion, metastasis and support of cancer development and growth." (PMID 34683450, 2021). "To further clarify the potential role of BDNF in cancer immunity, we estimated the correlation of BDNF expression levels with chemokines and chemokine receptors, which were best known for their ability to orchestrate the proper movement of immune cells." (PMID 34777634, 2021). "All selected miRNAs showed overlap in regulation in pathways associated with cancer, IL-2 signaling, TGF-β signaling as well as BDNF signaling pathway." (PMID 35145424, 2021). "High mRNA expression of BDNF was noted in many cancer lines, especially those originating from the bone, pancreas, and pleura, whereas the relatively low expression was observed in the breast, intestine, and hematopoietic and lymphoid organs." (PMID 34777634, 2021). "Brain derived neurotrophic factor (BDNF) is a neurotrophin involved in neural and metabolic diseases, but it is also one of the crucial factors in cancer development and metastases." (PMID 34395067, 2021). "BDNF expression and its influence on patient prognosis were explored based on The Cancer Genome Atlas, Cancer Cell Line Encyclopedia, Genotype-Tissue Expression, and Kaplan-Meier plotter." (PMID 34777634, 2021). "First, the profile of BDNF was estimated in human cancer cell lines, human normal tissues, and multiple cancer types." (PMID 34777634, 2021). "ANA -12 treatment reduced cancer cell viability, induced cell cycle arrest and, with human recombinant BDNF, reduced colony formation." (PMID 34395067, 2021). "The enriched environment (EE) stimulates the hypothalamus to release BDNF, which enhances adaptive immunity and further affects the progression of cancer." (PMID 35003085, 2021). "BDNF and its high-affinity tyrosine kinase receptor, tropomyosin receptor kinase B (TrkB), have been demonstrated to be overexpressed in multiple cancers, such as neuroblastoma, oral, breast, lung, and colorectal cancer." (PMID 34777634, 2021). "Brain-derived neurotrophic factor (BDNF) is a critical member of the neurotrophin polypeptide superfamily that plays an important role in multiple cancers." (PMID 34777634, 2021). "All the selected miRNAs showed overlap in regulation in pathways associated with cancer, IL-2 signaling, TGF-β signaling as well as BDNF signaling pathway." (PMID 35145424, 2021). "They found that OSC19 and MDA1986 had high expression levels of TrkB, and BDNF treatment enhanced the migratory and invasive properties of the cancer cells." (PMID 34885121, 2021). "Thus, BDNF might also hold the risk of increasing cancer and other off target lateral effects." (PMID 32927875, 2020).
cancer (continued). "We also confirmed previous chronic pain, cancer surgery, pressure pain tolerance and BDNF (with almost statistical significance p = 0.051) as independent predictors of postoperative movement-evoked pain." (PMID 31914146, 2020). "Microenvironmental components and infiltrating inflammatory cells are able to provide mediators, such as TGF-β1 neurotrophins, as brain-derived neurotrophic factor, which transform epithelial cancer cells into EMT cells." (PMID 32059478, 2020). "BDNF acts as an antioxidant to protect neuronal cells against oxidative stress and attenuates oxidative stress in cancer cells." (PMID 32183322, 2020). "Brain-derived neurotrophic factor (BDNF), binding its high-affinity tyrosine kinase B receptor, has been shown to promote cancer progression and metastasis." (PMID 33294440, 2020). "In contrast, FIGN, HTRA3 and BDNF have been reported in cancer, EMT, invasion/migration process or poor outcome of patients, but our study for the first time links them to methylation status." (PMID 32971738, 2020). "BDNF is also expressed in tumors, e.g., osteosarcoma, and stimulates cancer growth and formation of metastasis through binding to TrκB as shown for breast cancer." (PMID 32927875, 2020). "BDNF and its receptor, TrkB, are also upregulated in breast, prostate, gastric, lung, and cervical cancers." (PMID 33322770, 2020). "In many types of cancers, BDNF and/or TrkB have been found expressed or in some cases over-expressed." (PMID 33096634, 2020). "BDNF can be produced by neurons, astrocytes, macrophages, fibroblasts and B lymphocytes and cancer cells, and exerts its effect mainly by acting on its receptors—with high affinity to tyrosine receptor kinase B (TrkB) and with low affinity on p75 receptor." (PMID 32183322, 2020). "The goal of this study was to determine the role of the BDNF Val66Met genotype on cancer-related fatigue in subjects with confirmed cancer diagnoses." (PMID 32848137, 2020). "In cancer BDNF has been shown to play a role in proliferation, invasion and metastasis in central nervous system, mammary, ovarian, pancreatic and uterine neoplasms." (PMID 32183322, 2020). "Hypomethylation of signal transduction-related genes BDNF and CALCB have the potential to lead to a myriad of cellular responses associated with cancer such as cell growth and proliferation, angiogenesis, and inflammation." (PMID 32051475, 2020). "In these samples, BDNF antibody generated a specific immunostaining in cancer cells in the 75% of the samples." (PMID 33294440, 2020). "BDNF Val66Met was analyzed by polymerase chain reaction in 180 patients with confirmed cancer diagnoses." (PMID 32848137, 2020). "BDNF/TrkB signaling is activated in several cancers, including breast, colon, lung, pancreatic, and ovarian cancers, cutaneous melanoma, and oral squamous cell carcinoma (OSCC)." (PMID 32731498, 2020). "We previously demonstrated that neuronal overexpression of BDNF reproduces various effects of EE including systemic metabolism, adipose remodeling, immune modulations, cancer, and aging." (PMID 32007953, 2020). "Recently, TrkB and its ligand, BDNF, have been shown to be overexpressed in various types of cancer, such as cervical, breast, and colorectal cancer (CRC), and to be associated with their poor prognosis." (PMID 31941116, 2020). "Chemokine signaling is important for the transition from tangential to radial migration, and the expression of chemokine receptors is directly affected by BDNF–TrkB signaling in the central nervous system, as well as in disease states such as cancer." (PMID 31941661, 2020). "Here, BDNF and E2-treated astrocytes triggered BDNF protein synthesis, and knockdown of TrkB in cancer cells abolished this upregulation, demonstrating the existence of a similar positive feedback loop of BDNF/TrkB in cancer cells." (PMID 30796353, 2019).
cancer (continued). "Here we demonstrate that E2 promotes TNBC metastases by a novel mechanism involving E2-dependent paracrine and autocrine upregulation of BDNF, and subsequent activation of its receptor TrkB, expressed by cancer cells." (PMID 30796353, 2019). "Activation of TrkB promotes migration of neurons and invasion of cancer cells, thus we investigated if BDNF/TrkB activation promoted invasion in TNBC cells." (PMID 30796353, 2019). "Upregulation of cancer cell BDNF was required to promote full invasiveness of 4T1BR5 in response to CM-E2, and was observed in brain metastatic cells in E2-treated mice in vivo." (PMID 30796353, 2019). "Recently, it was reported that loss of miR-204 resulted in BDNF/TrkB overexpression and activation of the AKT/mTOR/Rac1 signaling pathway in cancer cells." (PMID 31480771, 2019). "Among the four largest clusters with >100 reported PPI-based MPP communities, the cluster with 135 communities, such as BDNF/NT-3 growth factor receptor (encoded by NTRK2), was broadly linked to the most pathways relevant to cancer hallmarks." (PMID 31311925, 2019). "Among them, NGF and BDNF are the most important NTs studied in the context of reproduction and cancer." (PMID 31608227, 2019). "It has also been demonstrated that as cancer patients undergo chemotherapy, changes in plasma BDNF levels differ between BDNF genotypes." (PMID 30382534, 2019). "Secreted pro-BDNF is cleaved to BDNF by the tissue plasminogen activator (tPA)/plasmin protease system in the brain, suggesting that astrocytic BDNF reaches cancer cells within the brain niche as mature BDNF." (PMID 30796353, 2019). "Recent discovery of the role of BDNF in cancer suggests that understanding how BDNF orchestrates its diverse effects on genome dysregulation will also provide a new window on cancer chemotherapies." (PMID 31455240, 2019). "Genetic markers, such as BDNF Val66Met, should be incorporated in these prediction models once they have been validated in other cancer populations." (PMID 30382534, 2019). "In 4T1BR5 cells, there was a positive feedback loop whereby astrocytic BDNF induced cancer cell BDNF translation." (PMID 30796353, 2019). "BDNF, located on the short arm of chromosome 11 (11p13), is up-regulated in various human cancer types including NB." (PMID 31787850, 2019). "As these cells only differ in their ability to produce BDNF, this suggests that factors released by astrocytes in CM-E2 upregulate BDNF in cancer cells, promoting autocrine BDNF/TrkB activation." (PMID 30796353, 2019). "The p75NTR, NGF/TrkA (for ESCC), and BDNF/TrkB (for GC) have been extensively researched in these cancers in an effort to develop better predictive markers." (PMID 30741921, 2019). "According to previous reports, a greater prevalence of pain occurs in patients with OSCC than in patients with other cancer types, and the BDNF/TRKB signaling pathway is involved in OSCC-induced pain." (PMID 29861866, 2018). "Similar observations were made for other cancers as an increased level of TrkB and BDNF as well as the downregulation of expression of E-cadherin were correlated with the invasion and metastasis of salivary adenoid cystic carcinoma cells." (PMID 30190671, 2018). "BDNF facilitates cancer metastasis via binding to its receptors, TrkB/ TrkC and/or p75NTR as demonstrated in breast, colorectal, clear cell renal cell carcinoma and non-small cell lung cancer (NSCLC)." (PMID 29334991, 2018). "Some Chinese medicinal herbs are able to enhance the BDNF-related metastatic potential of the interaction between cancer cells and endothelial cells." (PMID 28800782, 2017). "Consistent with this, short-term exposure of cancer-associated fibroblasts, mesenchymal stem cells, and osteoblasts to pH 6.8 promotes the expression of inflammatory and nociceptive mediators (NGF, BDNF, IL6, IL8, IL1b and CCL5)." (PMID 28903357, 2017).
cancer (continued). "In this article, the modulatory effects of BDNF on the interaction between cancer cells (MDA-MB-231) and endothelial cells (HUVEC) was investigated." (PMID 28604807, 2017). "TrkB, a potent anoikis suppressor, is overexpressed in several kinds of malignancies, and BDNF-mediated activation of TrkB (ligand binding to the receptor) contributes to anoikis resistance of cancer cells, including HCC." (PMID 28430645, 2017). "To our knowledge, we are the first to investigate the effect of Chinese herbal medicines on the BDNF-related metastatic potential of cancer-endothelial interactions." (PMID 28800782, 2017). "BDNF-induced TrkB activation confers antiapoptotic, tumorigenic, invasive, and metastatic capacities upon cancer cells." (PMID 27458153, 2016). "‘Cancer’ was the most represented function, with 57 genes, including BDNF, NR2C2 and CADPS2 (1.99 × 10–8 < P < 1.23 × 10–2)." (PMID 26999292, 2016). "In bone metastatic gastric cancer, PTX3 knockdown using small interfering RNA significantly inhibited BDNF-induced interactions of cancer cells with osteoblasts." (PMID 27458153, 2016). "We detected significantly increased levels of BDNF transcripts in most cancer samples (4 of 5) compared with normal tissues." (PMID 27456333, 2016). "In contrast, the significant BDNF-pw were related to receptor binding, gene regulations of certain cells or organisms that were involved in cancer or physical health problems." (PMID 26091093, 2015). "to examine the precise role of BDNF/TrkB signaling in cancer, although we didn't clarify it in this study." (PMID 24801982, 2014). "We also used β5 integrin siRNA to examine the role of β5 integrin and found that it inhibited BDNF-induced cancer cell migration." (PMID 23874483, 2013). "BDNF and its receptor TrkB play key roles in neural development, and some studies have suggested a role for BDNF in cancer cell proliferation, survival, differentiation, and invasiveness." (PMID 23874483, 2013). "Previous studies have reported that BDNF is expressed in bone and cartilage tissues, and is able to increase cell migration and invasion activity in many human cancer cells." (PMID 23892595, 2013). "The expression levels of BDNF and TrkB mRNA have been demonstrated to be higher in human cancer cell lines than in normal tissues." (PMID 24255678, 2013). "Recent studies have suggested a major role for BDNF in cancer cell proliferation, survival, differentiation, and invasiveness." (PMID 23892595, 2013). "To explore the role of PI3K/Akt in cancer migration and integrin expression, we next investigated Akt Ser473 phosphorylation in response to BDNF treatment." (PMID 23874483, 2013). "The expression level and impact of brain-derived neurotrophic factor (BDNF) has been reported in several types of carcinomas, although how this protein exerts its effects remains to be identified." (PMID 24255678, 2013). "In addition to cancer cell migration and invasion, activation of BDNF/TrkB signaling may also contribute to evasion of apoptosis in miR-204 depleted cells as BDNF/TrkB overexpression has been linked with stabilization and activation of AKT resulting in decreased apoptosis." (PMID 23285024, 2012). "Our results reveal that loss of miR-204 results in BDNF overexpression and subsequent activation of the small GTPase Rac1 and actin reorganization through the AKT/mTOR signaling pathway leading to cancer cell migration and invasion." (PMID 23285024, 2012). "Our findings reveal that loss of miR-204 results in BDNF/TrkB overexpression and concomitant activation of the AKT/mTOR/Rac1 signaling pathway, leading to actin reorganization during cancer cell migration and invasion." (PMID 23285024, 2012). "One interesting result regarding the reduction in Bim expression mediated by BDNF is that Bim has been reported to regulate anoikis, apoptosis induced by detachment, in various cancers." (PMID 22276165, 2012).